RARG (retinoic acid receptor gamma)
Diseases named in the same sentence as RARG in open-access papers (continued):
Sharing a sentence is not in itself a finding about the gene and the disease.
childhood cancer (5 papers, 2021 to 2025). "A notable example is a GWAS in 280 European-ancestry patients (32 cases vs. 248 controls) with childhood cancer, which identified a non-synonymous variant (rs2229774, S427L) in RARG as highly associated with Doxo-induced cardiotoxicity." (PMID 41446145, 2025). "An earlier study of 280 patients treated for childhood cancer identified a single SNP (P < 5.9x10-8) in the RARG gene associated with cardiotoxicity in the original cohort and two replication cohorts." (PMID 38416769, 2024). "Pharmacogenomic testing is recommended for childhood cancer patients with indication for the anthracyclines daunorubicin and doxorubicin for specific variants of RARG, SLC28A3 and UGT1A6*4." (PMID 35872888, 2022). "Indeed, it would be interesting to add a genetic screening to the clinical guidelines for patients diagnosed with childhood cancer targeting the RARG- rs2229774 risk variant, the SLC28A3-rs7853758 protective variant or the harmful union of the P2RX7-rs208294 and P2RX7-rs3751143 variants." (PMID 40413218, 2025).
colon cancer (5 papers, 2017 to 2024). "The interaction between RARγ and β-catenin is more complex because Wnt/β-catenin signaling regulates the expression of Yes-associated protein (YAP) as shown for colon cancer cells." (PMID 39273194, 2024). "YAP is a coactivator of RARγ and acted via RAREs to reinforce stem cell traits within HT-29 colon cancer cells, including self-renewal." (PMID 39273194, 2024). "RARγ interacts with YAP in the cytoplasm of colon cancer cells and the interaction between RARγ and YAP could be significantly enhanced after RA treatment." (PMID 31590252, 2019). "RARγ was then transfected into Bel-7402 liver cancer cells and SW480 colon cancer cells, both with very low endogenous RARγ." (PMID 28336971, 2017).
emphysema (5 papers, 2015 to 2022). "RARγ has been associated with elastin production, and its reduced expression appears to be associated with the development of emphysema." (PMID 26462767, 2015). "Palovarotene, a retinoic acid receptor gamma (RARγ) agonist, previously used in patients with emphysema, can inhibit the chondrogenesis phase in HO formation." (PMID 36522666, 2022). "Exogenous ATRA, RARα and RARγ agonists and 4-oxo RA can induce alveolar regeneration in adult rats displaying emphysema and partially rescue their phenotype." (PMID 31963453, 2020). "For example, palovarotene, a retinoic acid receptor gamma (RAR-γ) agonist developed for use in emphysema, was found to be efficacious in an animal model of fibrodysplasia ossificans progressiva (FOP), and is now in phase 3 clinical trials." (PMID 33658983, 2020). "One of the RARγ class drugs is palovarotene, a highly specific RARγ agonist that has already been evaluated in another clinical trial for α-1-antitrypsin-induced emphysema, and its safety profile has been well-characterized." (PMID 32887348, 2020). "Moreover, RARγ agonist’s administration promotes alveolar repair in an animal model of emphysema." (PMID 31963453, 2020).
fibrodysplasia ossificans progressiva (5 papers, 2019 to 2025). Fibrodysplasia ossificans progressiva (FOP) is a severely disabling heritable disorder of connective tissue characterized by congenital malformations of the great toes and progressive heterotopic ossification that forms qualitatively normal bone in characteristic extraskeletal sites. "Palovarotene is a synthetic retinoic acid receptor γ (RARγ) agonist that was first described in studies several years ago1 and was recently approved for the treatment of fibrodysplasia ossificans progressiva (FOP)." (PMID 39677926, 2025). "These preclinical studies led to a clinical trial investigating Palovarotene, a RARγ agonist as a potential treatment for Fibrodysplasia ossificans progressiva (FOP), which is characterized by heterotopic bone formation leading to progressive loss of mobility and function." (PMID 32294904, 2020).
liver cancer (5 papers, 2016 to 2025). An epithelial or non-epithelial malignant neoplasm that arises from the liver. "RARγ-dependent activation of PI3K/AKT pathway was described in several liver cancer cell lines including HepG2 and QGY-770311." (PMID 28336971, 2017). "Furthermore, we examined gene expression data from Oncomine, and found that RARγ mRNA levels are significantly upregulated in HCC tissues compared with liver cancer precursor tissues." (PMID 27756432, 2016). "For examples, the dynamic expression of RARB, RARG similar with RARA can control the development and proliferation of liver cancer and HOXB8 from HOX family can play a prominent role as a brain tissue biomarker." (PMID 29033978, 2017). "Seven TFs (FOXA1, FOXA2, RARG, STAT4, MEF2C, SOX18, and GXS2) have been identified to be likely to affect the metabolism, development, differentiation and proliferation of liver cancer in previous studies." (PMID 29033978, 2017). "The effects of acacetin on AKT inhibition and apoptosis were also reproducible in all other liver cancer cell lines that expressed high level of RARγ (data not shown)." (PMID 28336971, 2017).
lung carcinoma (5 papers, 2015 to 2025). "Dysregulation of RARA and RARG has also been linked to cell survival and chemoresistance in other solid tumors, including skin and lung cancers." (PMID 41155227, 2025). "However, RARβ and perhaps also RARγ and RXRβ were repressed in a high proportion of lung cancer patients, suggesting the association of lung carcinogenesis with the loss of expression of one or more receptors." (PMID 35631448, 2022). "It is notable that this study used a regimen that combined an RARγ agonist with checkpoint blockade to repress lung cancer growth." (PMID 37689790, 2023). "Taken together, the findings reported here provide a strong rationale to explore efficacy of combining an RARγ agonist with immune checkpoint blockade in lung cancer therapy." (PMID 37689790, 2023). "A study reported an in vitro increased expression of RARα and RARγ and reduced RARβ in lung carcinoma cell lines." (PMID 35631448, 2022). "A report showed that RARβ is increased in expression in lung cancer cell lines, and CD437, which binds selectively to nuclear RARγ, can hamper cell growth and cause apoptosis in ATRA-resistant NSCLC cells." (PMID 35631448, 2022). "Both RARα and RARγ were expressed in the examined human and murine lung cancer cell lines." (PMID 37689790, 2023). "The precise role for RARγ in cigarette smoke-induced lung cancer needs further investigation." (PMID 26462767, 2015). "It was reasoned that IRX4647, an RARγ selective agonist, would augment activity of immune checkpoint inhibitors and overcome resistance to anti-PDL-1 treatments in a syngeneic lung cancer model (344SQ in 129sv mice)." (PMID 37689790, 2023). "IRX4647-treatment did not appreciably affect in vitro lung cancer growth, despite RARγ expression." (PMID 37689790, 2023).
ovarian carcinoma (5 papers, 2008 to 2025). A malignant neoplasm originating from the surface ovarian epithelium. "A high level of expression of RARγ mRNA was associated with FIGO stage III/IV ovarian cancer and proposed as an independent predictor of poor overall survival." (PMID 40362593, 2025). "From in vitro studies, the proliferation and colony formation capacity of ovarian cancer cell line cells were suppressed by downregulation of RARγ, and tumour growth by cell line cells in nude mice was significantly reduced by knockdown of RARγ." (PMID 40362593, 2025). "For ovarian cancer cells, high expression of RARγ accelerated cancer progression by promoting cell proliferation." (PMID 40362593, 2025). "High-level RARγ expression within ovarian cancer cells was related to FIGO stages III–IV and a survival time of <5 years." (PMID 37569466, 2023). "For the ovarian cancer cell line cells, a high level of RARγ expression regulates cell proliferation because knockdown reduces the level of Ki-67 and the proliferating cell nuclear antigen." (PMID 36768694, 2023). "This study is also the first to report that RARG can act as an oncogene to promote ovarian cancer progression." (PMID 36523991, 2022). "Cell biology experiments showed that RARG knockdown attenuated the proliferation and clonogenesis of ovarian cancer cells in vitro, and knocking out RARG protein expression significantly inhibited the growth of ovarian tumor tissue in vivo." (PMID 36523991, 2022). "The results indicated that the progression of ovarian cancer can be regulated through multiple pathways by high expression level of RARG." (PMID 36523991, 2022). "We applied qRT−PCR and immunohistochemistry to additionally comfirm the differences in the mRNA expression levels and protein expression levels of RARG between ovarian cancer tissues and adjacent normal tissues." (PMID 36523991, 2022). "To explore the differences in immune cell infiltration between high and low RARG expression groups, we first mapped the immune cell infiltration of each ovarian cancer patient in the TCGA cohort." (PMID 36523991, 2022). "The results showed mRNA expression levels of RARG in ovarian cancer tissues were higher than adjacent normal tissues." (PMID 36523991, 2022). "This study improves our understanding of the clinico-pathological significance and molecular pathogenesis of OC, we also need to conduct further research and deeply explore the mechanism of RARG in promoting the proliferation of ovarian cancer cells." (PMID 36523991, 2022). "The GSEA enrichment analysis revealed that RARG was involved in ovarian cancer progression through multiple pathways." (PMID 36523991, 2022). "Decreased RARγ activity has been implicated in ovarian cancer, and AHPN (CD437), an RARγ agonist, has been shown to induce apoptosis and inhibit growth of ovarian tumor cell lines as well as transplanted tumors in nude mice." (PMID 18398471, 2008). "The level of RARγ protein was also higher in ovarian cancer tissue than in adjacent normal tissue." (PMID 40362593, 2025). "RARγ plays an important role in ovarian cancer cell proliferation." (PMID 36768694, 2023). "Furthermore, in order to clarify the promoting effect of RARG on ovarian cancer cells in vivo, we used sh-RARG group (n=5) and sh-Scramble group (n=5) of A2780 cells to inoculate nude mice subcutaneously." (PMID 36523991, 2022). "It suggested that RARG might affect the progression of ovarian cancer cells by participating in transcriptional regulation." (PMID 36523991, 2022). "In this study, bioinformatics analysis showed that the mRNA level of RARG was increased in ovarian cancer tissues, and high expression of RARG was an independent predictor of poor prognosis, suggesting that RARG could be used as a molecular marker for the diagnosis and prognosis of OC." (PMID 36523991, 2022). "However, the role of RARG in the occurrence and development of ovarian cancer is still unclear." (PMID 36523991, 2022).
ovarian carcinoma (continued). "In in vitro experiments, the proliferation and colony formation capacity of ovarian cancer A2780 and SKOV3 cell line cells was suppressed by down-regulation of RARγ expression." (PMID 36768694, 2023).
embryonal carcinoma (4 papers, 2009 to 2023). A non-seminomatous malignant germ cell tumor characterized by the presence of large germ cells with abundant cytoplasm resembling epithelial cells, geographic necrosis, high mitotic activity, and pseudoglandular and pseudopapillary structures formation. "Studies have examined the effect of treating P19 and F9 embryonal carcinoma cells with a combination of the synthetic RARα- and RARγ-selective agonists Am80 and CD666, respectively." (PMID 37082619, 2023). "The hypothesis that in vitro and in vivo pathways are comparable is supported by significant up-regulation of RARα and RARβ mRNA, but rapid down-regulation of RARγ and RXRγ mRNA during RA-induced neuronal differentiation of mouse embryonal carcinoma cells." (PMID 19642999, 2009). "Finally, it is worth mentioning that these findings performed in P19 embryonal carcinoma cells were also confirmed in mouse embryonic stem cells, confirming the potency of the synergistic action of both RARβ and RARγ agonists to lead to neuronal cell specialization." (PMID 38137880, 2023). "In keeping with a restricted expression of RARγ within primitive cells, the binding sites for RAR/RXR dimers within undifferentiated F9 embryonal carcinoma cells coincided with loci that are targeted by transcription factors that are important to pluripotency (SOX2, NANOG, and POU5f1)." (PMID 37082619, 2023).
neuroblastoma (4 papers, 2011 to 2025). Neuroblastoma (NB) is the most common solid, extracranial childhood tumor. "Supporting this notion, a previous study demonstrated that suppression of c-Src signaling inhibited RARγ-mediated neuritogenic differentiation in neuroblastoma cells." (PMID 39744424, 2025). "RNA sequencing results showed a synergistic induction of genes associated with RA signaling (RARB, RARG), neuronal differentiation (HOXC5, PBX1), and chromatin remodeling (RYBP, JADE2), which are positively correlated with favorable prognosis in neuroblastoma." (PMID 39711563, 2024). "Previous reports indicated that increased RARγ expression suppresses the malignant phenotype and alters the differentiation potential of human neuroblastoma cells, here we detected ATRA or bortezomib alone can upregulate RARγ expression, while no further increase with combined treatment." (PMID 22087283, 2011).
Osteochondroma (4 papers, 2020 to 2025). A common, benign cartiliginous neoplasm arising from the metaphysis of bone. "The tested human chondrosarcoma cell xenograft was more sensitive to RARγ agonists than that were mouse osteochondromas." (PMID 39062860, 2024). "The actions of the retinoic acid nuclear receptor gamma (RARγ) agonist, palovarotene, on pre-existing osteochondromas were investigated using a mouse multiple osteochondroma model." (PMID 39062860, 2024). "Nanoparticle (NP)-based local delivery of the RARγ agonist also inhibited the growth of osteochondromas at an early stage (Control: 0.52 ± 0.11 mm3; NP: 0.26 ± 0.10, p = 0.008)." (PMID 39062860, 2024). "This study was performed to examine the application of palovarotene and other RARγ agonists for the treatment of osteochondromas." (PMID 39062860, 2024). "In summary, this study demonstrated that RARγ agonists target human osteochondroma cells and induce various biological responses including proteoglycan degradation and cell death induction." (PMID 32294904, 2020). "Human osteochondromas were obtained during surgery and subjected to RARγ agonists treatment via explant culture followed by histological and transcriptome analysis." (PMID 32294904, 2020). "To compare the effect of RARγ agonists between osteochondromas and human growth plate chondrocytes, we obtained chondrocytes from polydactyly samples, since the acquisition of enough amounts of chondrocytes from normal growth plate is limited." (PMID 32294904, 2020). "To understand how RARγ agonist treatment affects biological functions in osteochondroma cells, we performed transcriptome analysis." (PMID 32294904, 2020). "These biological responses induced by RARγ agonists treatment suggest the possibility that RARγ agonists affect mature osteochondromas, by inducing both destruction of their extracellular matrix structure and stimulating cell death." (PMID 32294904, 2020). "Osteochondroma explants were treated with RARγ agonists (NRX204647 or Palovarotene) for 4 or 7 days." (PMID 32294904, 2020). "Although these results are promising, it would be too early to reach definitive conclusions regarding the pharmacological effect of RARγ agonists on human osteochondromas, since the number of tested samples was limited." (PMID 32294904, 2020). "In order to offer efficient and safe therapies in the upcoming future for MO, understanding the molecular actions of RARγ agonists on human osteochondromas is vital." (PMID 32294904, 2020). "In this pathway, IRF-1 was up-regulated by RARγ agonist treatment in both osteochondroma explant cultures and polydactyly chondrocytes." (PMID 32294904, 2020). "Osteochondroma specimens were obtained during surgery, subjected to explant culture and were treated with RARγ agonists or vehicles." (PMID 32294904, 2020). "The purpose of this study was to evaluate the pharmacological effects of the RARγ agonists on human osteochondromas." (PMID 32294904, 2020). "The third aim is to investigate alterations of the molecular pathways in palovarotene-treated osteochondroma chondrocytes because elucidation of molecular pathways affected by the RARγ agonist should be valuable in developing alternative drugs for osteochondromas." (PMID 39062860, 2024). "In addition, we demonstrated that RARγ agonists stimulated the signal transducer and activator of the transcription 3 (Stat3) signaling pathway in osteochondroma cells." (PMID 39062860, 2024). "Furthermore, local application of the RARγ agonists inhibited osteochondroma growth for a limited period of time." (PMID 39062860, 2024). "The second aim is to determine whether local application of the RARγ agonist can inhibit osteochondroma growth, minimizing systemic adverse effects." (PMID 39062860, 2024). "The purpose of this study was to examine the action of RARγ agonist in human osteochondromas." (PMID 32294904, 2020).
Osteochondroma (continued). "Previous studies have demonstrated retinoic acid receptor gamma (RARγ) agonists to inhibit ectopic endochondral ossification, therefore we hypothesize that RARγ agonists can target on established osteochondromas." (PMID 32294904, 2020). "Together, these findings suggest that RARγ agonist may exert anti-tumor function on osteochondromas by inhibiting matrix synthesis, promoting cartilage matrix degradation and stimulating cell death." (PMID 32294904, 2020). "Therefore, we can assume that this study shows the sensitivity of osteochondroma chondrocytes to RARγ agonists." (PMID 32294904, 2020). "Since RARγ agonist strongly affects the function of mouse growth plate chondrocytes and inhibits the formation of osteochondromas in mice, we hypothesized that RARγ agonist can act on established human osteochondromas." (PMID 32294904, 2020). "Furthermore, mechanistic studies of RARγ agonists on inhibition of HO and osteochondromas also focused on chondrogenesis in rodent cells." (PMID 32294904, 2020). "In addition, preclinical studies have also demonstrated that stimulation of RARγ suppresses chondrogenesis and osteochondroma formation in MHE mouse models via BMP signaling inhibition." (PMID 32294904, 2020). "However, the findings support the hypothesis that RARγ agonists exert anti-tumor function on osteochondromas and encourages current and future studies on the development of pharmacological therapy for osteochondromas." (PMID 32294904, 2020). "RARγ target genes, TGM2 and CYP26B were up-regulated in osteochondromas." (PMID 32294904, 2020).